INCR1 (interferon stimulated noncoding RNA 1)
Gene: Long non-coding RNA gene on chromosome 9 (5,457,477 to 5,629,780, reverse strand). Ensembl gene ENSG00000286162.
Diseases named in the same sentence as INCR1 in open-access papers:
INCR1 is named in the same sentence as 7 diseases in open-access papers, as found by Europe PMC text mining. Sharing a sentence is not in itself a finding about the gene and the disease. The quoted sentences say what the papers report.
glioblastoma (3 papers, 2023 to 2025). The most malignant astrocytic tumor (WHO grade IV). "The bulk RNA sequencing analysis of patient-derived glioblastoma cell lines activated by IFN-γ revealed that lncRNA INCR1 was the most upregulated non-coding RNA." (PMID 37736898, 2023). "Knockdown of lncRNA INCR1 in the glioblastoma cell line led to inhibition of IFN-γ, and PD-L1 which allows the cytotoxic activity of T cells in vivo." (PMID 37736898, 2023). "Furthermore, INCR1 knockdown significantly reduced PD-L1 expression and increased cytotoxic T cell function in the context of glioblastoma." (PMID 40449595, 2025).
tumor (7 papers, 2021 to 2025). "Targeting INCR1 reduces more immunosuppressive molecules than PD-L1 and increases tumor cell susceptibility to IL12-mediated immune cell cytotoxicity." (PMID 40035950, 2025). "In addition, knocking out INCR1 made tumor cells susceptible to the killing effect of T cells, thereby making improvements in CAR-T." (PMID 35222443, 2022). "Most importantly, INCR1 silencing improved IL12-mediated PBMC cytotoxicity against tumor cells compared to monoclonal antibodies targeting PD-1 or PD-L1." (PMID 40035950, 2025). "We have recently identified the interferon-stimulated noncoding RNA 1 (INCR1) as a novel lncRNA transcribed from the PD-L1 locus and showed that INCR1 is highly inducible in tumor cells stimulated with IFNγ." (PMID 40035950, 2025). "Control and stable INCR1 knockdown cells were allowed to form 3D tumor spheroids on an ultralow attachment plate and then co-cultured with unstimulated or IL12-stimulated PBMCs." (PMID 40035950, 2025). "One possible reason for the increased PBMC cytotoxic effects is reduced T-cell exhaustion when INCR1 is silenced in tumor cells." (PMID 40035950, 2025). "The data suggest that the AhR is a key mediator of tumor immunosuppression through regulation of IFN-induced INCR1 and JAK/STAT signaling and, thereby, expression of immune checkpoints." (PMID 40449595, 2025). "In both PDGCs, INCR1 was upregulated in response to IL12 treatment when tumor cells were co-cultured with PBMCs." (PMID 40035950, 2025). "In this study, we showed that tumor tissues from GBM patients treated with IL12 gene therapy presented an upregulation of the lncRNA INCR1 compared to the tumor tissues of the same patients before the IL12 treatment." (PMID 40035950, 2025). "While IL12 treatment activated the PBMC cytotoxic effects against both control and INCR1 knockdown tumor cells, we found a significant increase in the cytotoxicity of PBMCs on INCR1 knockdown tumor cells compared to control." (PMID 40035950, 2025). "RNAscope in situ hybridization was performed to analyze INCR1 and PD-L1 expression in tumor tissues from GBM patients pre- and post-IL12 gene therapy." (PMID 40035950, 2025). "Hybridization of the tumor tissues with an INCR1 probe showed an increased signal in all GBMs post-IL12 treatment compared to the signal before IL12 therapy." (PMID 40035950, 2025). "In detail, downregulation of INCR1 in several tumor cell lines led to suppression of PD-L1 expression, and tumor spheres with INCR1 downregulation were more sensitive to CD8 + T cell-mediated killing." (PMID 34496886, 2021). "While targeting INCR1 increased immune-mediated tumor cell death, the effects of INCR1 silencing on the efficacy of IL12 immunotherapy remain unknown." (PMID 40035950, 2025). "Moreover, lncRNAs are involved in tumor-associated immune regulation, and the IFN-associated lncRNA INCR1 binds hnRNPH1, thereby preventing it from negatively affecting the expression of neighboring genes PD-L1 and JAK2." (PMID 36118202, 2022). "INCR1 knockdown made tumor cells more sensitive to cytotoxic T cell-mediated killing." (PMID 35222443, 2022). "Furthermore, lncRNA IFN-stimulated noncoding RNA 1 (INCR1), transcribed from the PD-L1 locus, is correlated with PD-L1 expression levels in tissues and is involved in regulation of tumor IFNγ signaling." (PMID 34496886, 2021). "Since we previously found that INCR1 regulates the expression of several immunosuppressive genes, we hypothesized that silencing INCR1 would increase PBMCs’ cytotoxic activity against tumor cells in response to IL12 stimulation." (PMID 40035950, 2025). "INCR1 and PD-L1 expression was upregulated in tumor tissue from GBM patients treated with IL12 gene therapy compared to the tumor tissue of the same patients before the IL12 treatment." (PMID 40035950, 2025). "Knockdown of INCR1 repressed IFN-γ-stimulated genes (ISGs) and increased T cell-mediated killing of tumor cells." (PMID 37346034, 2023).
tumor (continued). "Therefore, molecules that control INCR1 and HNRNPH1 expression and/or function are likely to contribute significantly to the regulation of tumor immunity." (PMID 40449595, 2025). "To investigate the transcriptional profile of the lncRNA INCR1 in GBM patients treated with IL12 immunotherapy, we performed RNAscope in situ hybridization on tumor tissues from five GBM patients (Pt10, Pt17, Pt37, Pt38, Pt39) before and after administration of IL12." (PMID 40035950, 2025). "While INCR1 serves as an inhibitory target to promote IFN-γ response and T cell activity, another cancer immunogenic lncRNA, lncRNA inducing MHC-I and immunogenicity of tumor (LIMIT), has been identified recently." (PMID 37346034, 2023).
cancer (1 paper, 2025). A tumor composed of atypical neoplastic, often pleomorphic cells that invade other tissues. "As previously reported in other cancers, IFNγ significantly increased INCR1 levels (third bar)." (PMID 40449595, 2025). "Finally, we sought to confirm that INCR1 regulates components of the IFNγ-induced JAK/STAT pathway and the resulting expression of immune checkpoints IDO1, CD274, and PDCD1LG2 in human LUAD cells, as shown in other cancer types." (PMID 40449595, 2025).
INCR1 also shares sentences with these, for which no sentence is quoted: breast adenocarcinoma (1 paper); glioma (1); lung carcinoma (1); melanoma (1).